SOCS3 (suppressor of cytokine signaling 3)
Diseases named in the same sentence as SOCS3 in open-access papers (continued):
Sharing a sentence is not in itself a finding about the gene and the disease.
cancer (continued). "The expression of SOCS3 might have an impact on the high-risk smokers have for the development of cancer, in the lungs and elsewhere." (PMID 38533493, 2024). "Tests of predicted functional polymorphisms in HNSCC for SOCS3, have been conflicting; rs2280148 located at the 3′-untranslated region, indicated a predicted increase in the risk for this cancer, while rs8064821 located in the promoter region was associated with an decreased risk." (PMID 35844493, 2022). "Furthermore, SOCS3 expression levels were associated with immunotherapy or chemotherapy for numerous types of cancer." (PMID 35600392, 2022). "The results showed that SOCS3 was associated with benign tumors, cancers, nervous system diseases, respiratory or thoracic diseases, genetic diseases, endocrine system diseases, nutritional or metabolic diseases, immune system diseases, and gastrointestinal diseases." (PMID 35600392, 2022). "Alterations in SOCS3 gene expression profiles may be associated with a poorer prognosis in the majority of cancers." (PMID 35600392, 2022). "For example, the activation of FXR by GW4064 inhibits leptin and its target genes induced by cancer-associated fibroblasts (CAFs) while increasing the expression of suppressor of the cytokine signalling 3 (SOCS3) that lead to inhibition of cell growth and invasion." (PMID 35006466, 2021). "Furthermore, reduced expression of SOCS3 has been observed in various human cancers and is associated with constitutive STAT3 activation." (PMID 24757565, 2014). "However, the pathogenesis of SOCS3 in various types of cancer and whether there is a common molecular mechanism between these different types of cancer in regulating the pathogenic effects and treatment responses remain to be further studied." (PMID 35600392, 2022). "Subsequently, potential cancer-associated miRNA clusters upstream of ANGPTL1, SOCS3, ACACB, and EHHADH were predicted via integrated cross-analysis using multi-databases, including miRDB, TargetScan, RNAInter, and miRWalk." (PMID 40426998, 2025). "The dysregulation of SOCS3 expression is associated with aberrant JAK/STAT signaling, contributing to the development and progression of several cancers." (PMID 40310419, 2025). "Aberrant STAT hyperactivation and consequent SOCS1 or SOCS3 intervention is observed in immune-mediated inflammatory diseases and malignancies of the skin." (PMID 38975347, 2024). "In comparison, the expression of suppressors of cytokine signaling (SOCS), especially SOCS3, was overexpressed in cancer, suggesting the presence of a regulatory feedback system that controls JAK/STAT signaling in the investigated cancers." (PMID 38979413, 2024). "Activation of STAT3 by JAK leads to transcriptional induction of the JAK inhibitor SOCS3 by STAT323, suggesting that STAT3 activity can oscillate in JAK-activated cancer cells and EGFR-mutated cancer cells." (PMID 38760429, 2024). "In this study, we explored the expression pattern and prognostic performance of SOCS3 in pan-cancer and its relationship with immune cell infiltration." (PMID 37025997, 2023). "The SOCS3 expression pattern and its relationship with the immune response in pan-cancer was investigated using multiple methods." (PMID 37025997, 2023). "Meanwhile, we also found that SOCS3 was positively correlated with main immune cell infiltration in almost each cancer type, especially in COAD." (PMID 37025997, 2023). "Apart from Raf and MEK, PKCγ can interact with ERKthat triggers cancer cells proliferation through cyclin D1.In cancer, SOCS3 acts as a suppressor." (PMID 37344815, 2023). "Mouse model research illustrated that SOCS3 mediated the proliferation and hyperplasia of the crypt and the transformation of inflammation into cancer in the colon." (PMID 37025997, 2023). "Aberrant methylation of SOCS3, a tumor suppressor gene, has been observed in several types of human cancer." (PMID 37762031, 2023).
cancer (continued). "We used the ROC plotter website to investigate the effects of SOCS3 expression on chemotherapy response in various types of cancer." (PMID 35600392, 2022). "In particular, SOCS1 and SOCS3, as potent inhibitors of JAKs, were reported to be played a critical role in various malignant processes, such as in cancers." (PMID 35184640, 2022). "DFS analysis displayed the relationship between upregulation of SOCS3 expression levels and poor prognosis for TCGA cancer types, including ACC (p=0.049), GBM (p=0.012), LGG (p=0.0067), and STAD (p=0.041)." (PMID 35600392, 2022). "We used the cBioPortal database to compare the types and frequencies of genetic changes in the SOCS3 gene in the different types of cancer." (PMID 35600392, 2022). "Inhibition of miR-92a or SOCS3 attenuated the sphere formation capacity, decreased expressions of stemness-related proteins, and inhibited the proliferation of cancer stem-like cells." (PMID 35184640, 2022). "Another promising target for gene editing to boost cancer immunotherapy is the Suppressor of cytokine signaling 3 (SOCS3)." (PMID 35449580, 2022). "At this time, SOCS3 enters into action and, to prevent over-invasion of cancer cells, in cooperation with Interleukin 6, provides conditions for strengthening the immune system and inflammatory responses." (PMID 35928368, 2022). "We found that SOCS3 was involved in cancer development primarily through the JAK/STAT signaling pathway and cytokine receptor activity." (PMID 35600392, 2022). "Some BIIGs were upregulated in multiple cancer types: Top2a, Mki67, Rrm2, Mcm6, and Spp1 were upregulated in more than eight cancer types, while Emp1, Ptx3, and Socs3 were upregulated in seven cancer types." (PMID 36605216, 2022). "Atypical SOCS1 and SOCS3 expression in established tumor cell lines and also at advanced clinical stages of cancer is considerably variable." (PMID 35844493, 2022). "SOCS3 expression was also shown to have certain effects on the response to chemotherapy and immunotherapy in several types of cancer, and additional experiments are required to further elucidate the mechanisms involved." (PMID 35600392, 2022). "The Oncomine website was employed to compare the mRNA expression levels of SOCS3 between various types of cancer and the corresponding healthy samples." (PMID 35600392, 2022). "Some BIIGs were downregulated in various cancers, especially Il1r1, Srgn, Emp1, Ptx3, Socs3, and Cebpd, which were downregulated in at least seven cancer types." (PMID 36605216, 2022). "The protein expression levels of SOCS3 in cancer tissues and the corresponding normal samples (medium expression and low expression) were explored via the Human Protein Atlas database." (PMID 35600392, 2022). "Results of qRT-PCR showed that expression of SOCS3 in cancer cell lines was lower than that in FHC cells." (PMID 35184640, 2022). "Our research showed that the expression of SOCS3 was relevant to immune infiltration in seven kinds of cancer, including CHOL, LGG, LIHC, PAAD, PRAD, SKCM, and STAD." (PMID 35600392, 2022). "Previous studies have validated that DNMT1 negatively regulates SOCS3 expression in several types of cancer cells." (PMID 34691358, 2021). "This axis can be inhibited by SOCS3 (suppressor of cytokine signaling 3); however, SOCS3 activity is often suppressed in cancer cells." (PMID 34063828, 2021). "Current reports have documented that miR-203 is a stemness-inhibiting miRNA owing to its modulation of stemness properties through regulating the expressions of various targets in different types of cancers, including SOCS3, survivin, Bmi-1, and GATA6." (PMID 34539782, 2021). "SOCS1 and SOCS3 have been the most extensively studied amongst the SOCS family members in relation to cancer and inflammation." (PMID 34439155, 2021). "SOCS1 and SOCS3 suppress cell growth and proliferation, and their expression is commonly downregulated in different types of cancer, including hematological malignancies such as ALL, CLL, and AML." (PMID 34439155, 2021).
cancer (continued). "TIMER was used to evaluate the association between SOCS3 and infiltrating immune cells, including CD4+ T cells, CD8+ T cells, B cells, cancer associated fibroblasts (CAFs), NK cells, macrophages and endothelial cells." (PMID 34120621, 2021). "SOCS3 has been extensively studied for over 20 years for their role in various diseases, especially in cancer." (PMID 32337016, 2020). "IHC representative images showed that SOCS3 is down‐regulated in cancer tissue compared with normal tissue." (PMID 31860165, 2020). "Recent studies have found that SOCS1 and SOCS3 genes are hypermethylated in various types of cancers." (PMID 32931454, 2020). "The mechanisms that disable SOCS1 and SOCS3 in human cancers are often epigenetic, mediated either by miRNAs, promoter methylation or protein phosphorylation." (PMID 31557897, 2019). "•Suppressor of cytokine signaling 3 (SOCS3) can be used as a control gene to evaluate the responsiveness of cancer cells to resistin treatment." (PMID 31417946, 2019). "Overall, 66 cancer tissues (91.7%) and 48 pericarcinoma tissues (66.7%) expressed SOCS-3 mRNA (RI, 0.373±0.284 and 0.376±0.247, respectively; t=0.067, P=0.947)." (PMID 30788302, 2018). "Research has shown that expression of SOCS-3 is decreased in many malignant tumor tissues and cell lines, such as head and neck squamous cell carcinoma, liver cancer, renal carcinoma, melanoma, and prostate cancer." (PMID 29662621, 2018). "In this study, we tested the effects of a newly-developed peptide, mimicking KIR and ESS domains of SOCS3 protein, in cultured transformed and healthy keratinocytes, following IL-22 stimulation, and in a cancer mouse model of SCC." (PMID 28445952, 2017). "Numerous reports showed that SOCS3 defects are responsible for sustained IL-6/STAT3 signaling in human cancers." (PMID 29326716, 2017). "The hypermethylation in the CpG (5′-Cytosine-phosphate-Guanine-3′) islands of the SOCS3 promoter can be a prognostic indicator in cancer development." (PMID 28179578, 2017). "The weak SOCS3 mRNA induction by IL-22 was confirmed in all the cancer cell lines examined (n = 2 for BCC and n = 5 for SCC), as compared to healthy keratinocyte strains (n = 5)." (PMID 28445952, 2017). "Suppressor of cytokine signaling (SOCS) 1 and SOCS3 are critical molecules in the development of cancers." (PMID 28228755, 2017). "In particular, SOCS1 and SOCS3 are strong inhibitors of JAKs and can play pivotal roles in the development and progression of cancers." (PMID 28228755, 2017). "Inhibition of leptin STAT3 signaling, achieved by administration of leptin antagonists, by leptin receptor monoclonal antibodies, or by upregulating SOCS3 would facilitate apoptosis and impede cancer cell growth." (PMID 26982332, 2016). "Increasing evidence supports a role of suppressor of cytokine signaling 3 (SOCS3) as a modulator of IEC turnover, balancing controlled repair and replenishment with excessive IEC proliferation predisposing to dysplasia and cancer." (PMID 25377316, 2015). "Several cancer-promoting genes were uperegulated (Ctgf, H19, Mmp12, Mybl1, Vnn1) while cancer inhibiting genes (Cish, Dkk4, Onecut1, Scara5, Socs3, Wif1) were suppressed." (PMID 26200659, 2015). "Recently, some evidence has also indicated that HDAC inhibitor suppression of JAK2/STAT3 signaling in cancer cells occurs through inducing the acetylation of histones connected to the promoter of SOCS3, a potent feedback inhibitor of JAK2/STAT signaling." (PMID 26636769, 2015). "Hypermethylation of the suppressor of cytokine signaling 3(SOCS3) promoter has been reported to predict a poor prognosis in several cancers including glioblstoma multiforme (GBM)." (PMID 24633048, 2014). "For instance, the anti-apoptotic proteins SOCS3, BCL2, and BIRC5 are known to be implicated in a number of cancers and to contain putative miR-203 binding sites within their 3'UTRs." (PMID 25004126, 2014).
cancer (continued). "In this regard, epigenetic silencing of SOCS3 has been found in various types of cancer, including lung cancer, head and neck squamous cell carcinoma, hepatocellular carcinoma and Barrett-associated esophageal adenocarcinoma." (PMID 24995504, 2014). "Reduced SOCS3 expression has also been observed in a variety of inflammation-related human cancers and cancer cell lines and correlated with strong STAT3 activity in these cells." (PMID 24757565, 2014). "A variety of studies have reported that hypermethylation of the SOCS3 promoter predicts poor prognosis in certain cancers, including GBM." (PMID 24633048, 2014). "Eight proliferation-associated genes including CCND1, CDK1, CDK6 and 26 apoptosis-regulating genes (e.g. SOCS3) were differently expressed between juvenile and cancer groups mostly supporting the pronounced cell growth in CRC." (PMID 24098334, 2013). "Recently, it has been reported that SOCS-3 acts as an endogenous inhibitor of pathological angiogenesis in mouse models of cancer and proliferative retinopathy." (PMID 24260222, 2013). "In this study, elevated Socs3 and Il-6ra likely resulted from the action of circulating IL-6 on skeletal muscle during cancer cachexia, as the rise in gene expression appeared to follow elevation of circulating IL-6." (PMID 22361433, 2012). "Overall, SOCS3 imunostaining intensity was low in epithelium from postmenopausal women and all tissues from the cancer patients." (PMID 20553623, 2010). "In HEC-1A and Ishikawa carcinoma cells, there was an upregulation of SOCS3 protein following the addition of 100 ng/ml IL11 compared to respective controls." (PMID 20553623, 2010). "Our in vitro studies identified that IL11 (from 1 ng/ml) stimulated SOCS3 protein abundance in non-carcinoma HES cells." (PMID 20553623, 2010). "Researches on human cancers have indicated that down-regulation of SOCS3 was correlated with aberrant methylation." (PMID 18507841, 2008). "SOCS1 and SOCS3 promoters are frequently methylated in primary tumors and cancer-derived cell lines, resulting in decreased expression of these negative regulators of Jaks and leading to sustained Jak activation." (PMID 17531096, 2007). "miR-142-3p targets the tumor suppressor FOXO1, promoting proliferation, and miR-4449 may influence STAT3 signaling by targeting SOCS3, as suggested in other cancers." (PMID 41462933, 2025). "Alongside STAT3, SOCS3 may interact with several other signaling pathways, affecting cancer diagnosis and prognosis." (PMID 38534772, 2024). "Based on the signal transduction pathways that IL-24 can activate in cancer cells, it is possible to speculate that IL-24 could induce the expression of a more stable and active truncated isoform of SOCS3." (PMID 37444474, 2023). "Taken together, our study comprehensively investigated the expression pattern, prognosis performance and relationship with immune cell infiltration of SOCS3 in pan-cancer, and showed that SOCS3 possessed value as a prognostic marker and target for immunotherapeutic intervention in different tumors." (PMID 37025997, 2023). "In pathological conditions such as cancer, SOCS3 either promotes or restrains disease progression." (PMID 37296634, 2023). "SOCS3 is an important regulator of cancer progression through a variety of signaling pathways." (PMID 37296634, 2023). "In conclusion, this study showed that SOCS3 is an immune-oncogenic molecule that may possess value as a biomarker for diagnosis, treatment, and prognosis of several types of cancer in the future." (PMID 35600392, 2022). "Whether SOCS3 exerts a role in the pathogenesis and therapeutic response of the different types of cancer via common molecular pathways remains to be determined." (PMID 35600392, 2022). "SOCS3 transcription is also activated by PPARγ to prevent IL-17-derived cancer growth." (PMID 35652039, 2022). "Finally, we investigated the genomic alterations of SOCS3 in 10,967 patients across TCGA Pan-Cancer Atlas Studies using the cBioPortal database." (PMID 35600392, 2022).
cancer (continued). "Prognostic value of SOCS3 in various cancers in PrognoScan database." (PMID 35600392, 2022). "Furthermore, GO and KEGG analysis were performed using these two groups to explore the effect of SOCS3 on cancer pathogenesis." (PMID 35600392, 2022). "In addition, SOCS3 methylation was negatively correlated with mRNA expression levels, worse prognoses, and dysfunctional T-cell phenotypes in various types of cancer." (PMID 35600392, 2022). "Furthermore, we found that the methylation status of SOCS3 was relevant to dysfunctional T-cell phenotypes and a poor prognosis in cancer." (PMID 35600392, 2022). "In summary, SOCS3 may be a potential marker for diagnosis, therapy, prognosis, and follow-up in several types of cancer." (PMID 35600392, 2022). "As demonstrated by inhibition, IL6-dependent STAT3 signaling may involve SOCS3 upregulation in E3-ligase-dependent proteasome activation with cancer cachexia, as well as with denervation." (PMID 35626644, 2022). "Expression of SOCS3 in different cancers on histological subtypes." (PMID 35600392, 2022). "CRC, cancer cell; CSCs, cancer stem cells; SOCS3, suppressor of cytokine signaling." (PMID 35184640, 2022). "The UALCAN website was used to explore the DNA methylation levels of SOCS3 in various cancers." (PMID 35600392, 2022). "Several studies have also found that SOCS3 is closely related to various types of cancer." (PMID 35600392, 2022). "Next, we used the TIMER2.0 to probe the expression of SOCS3 across a range of cancers." (PMID 35600392, 2022). "Therefore, we explored the potential molecular mechanisms of SOCS3 in the diagnosis, treatment, and prognosis of a range of cancers." (PMID 35600392, 2022). "Moreover, the prognostic values of SOCS3 in different types of cancer were also assessed using Kaplan–Meier Plotter databases." (PMID 35600392, 2022). "Furthermore, SOCS3 has often been identified to be silenced in various cancer cells owing to hypermethylated DNA at the domain of CpG island in its functional promoter region." (PMID 33659045, 2021). "Insome types of cancer, the role of SOCS3 seems controversial." (PMID 34450627, 2021). "In addition, CTCF dependent recruitment of EZH2 to the SOCS3 gene promoter is likely to participate in the epigenetic silencing of SOCS3 and in regulating its gene expression in cancer development." (PMID 34868904, 2021). "Manipulation of SOCS3 expression via the regulatory role of FXR might be expected to be a promising therapeutic option for cancer chemotherapy." (PMID 33164339, 2020). "In fact, accumulating studies have focused on the regulation of SOCS3 in cancers." (PMID 31222560, 2019). "Indeed, Runx1 stimulates Stat3 signaling in three epithelial cancer cell types through the transcriptional repression of a Stat3 inhibitor, SOCS3, which triggers cancer cell growth." (PMID 30026553, 2018). "Since it exerts key roles in the development of inflammatory diseases, viral infections, obesity and cancer, SOCS3 may be a biomolecular indicator for disease diagnosis and prognostic prediction." (PMID 29662621, 2018). "SOCS-1 and SOCS-3 may promote cancer development through promoting the proliferation of cancer cell." (PMID 30788302, 2018). "Hence, further investigation on the feasibility of SOCS1 and SOCS3 as potential cancer therapeutic targets has been conducted in many types of cancers." (PMID 28228755, 2017). "The roles of SOCS1 and SOCS3 in various types of cancer are still controversial." (PMID 28404963, 2017). "Importantly, increased levels of phospho-STAT3 were detected in patients with active UC, as well as in dysplasia and cancer, while a progressive decreasing trend of SOCS3 levels was observed from low-grade dysplasia to UC-CRC35." (PMID 28785079, 2017). "Among them, SOCS1 and SOCS3 are the critical molecules in the development of cancers." (PMID 28228755, 2017).